Y_RNA (Y RNA )
Gene: Miscellaneous RNA gene on chromosome 7 (77,041,647 to 77,041,748, forward strand). Ensembl gene ENSG00000201959.
Homologues: Orthologues: chimpanzee Y_RNA (99% identical), pig Y_RNA (75% identical). Paralogues in human: Y_RNA (100% identical), Y_RNA (97% identical), Y_RNA (93% identical), Y_RNA (92% identical), Y_RNA (90% identical), Y_RNA (89% identical), Y_RNA (87% identical), Y_RNA (85% identical), RNY3 (84% identical), RNY3P12 (84% identical), Y_RNA (84% identical), RNY3P1 (83% identical), and 98 more.